MSMO1 (methylsterol monooxygenase 1)
Diseases named in the same sentence as MSMO1 in open-access papers:
MSMO1 is named in the same sentence as 55 diseases in open-access papers, as found by Europe PMC text mining. Sharing a sentence is not in itself a finding about the gene and the disease. The quoted sentences say what the papers report.
breast carcinoma (7 papers, 2020 to 2025). "In breast cancer patients, targeting MSMO1 with siRNA increases the resistance to endocrine therapy." (PMID 36046654, 2022). "Moreover, the silencing of MSMO1 could enhance the sensitivity of breast cancer cells to paclitaxel and doxorubicin, presumably via the mTORC1 signaling pathway." (PMID 36078127, 2022). "The cholesterol biosynthesis enzyme MSMO1, a C4-methyl sterol oxidase in the Bloch pathway, has previously been shown to regulate EGFR signaling in breast cancer cells." (PMID 38488003, 2024). "We confirmed that MSMO1 was overexpressed in the PTX-res cells compared to the parental cells, while a GEPIA search revealed that its expression was significantly increased in breast cancer tissues compared to normal." (PMID 36078127, 2022).
dyslipidemia (5 papers, 2015 to 2022). "Studies have shown that MSMO1 plays an important role in the regulation of energy metabolism, obesity, and dyslipidemia." (PMID 34759952, 2021). "The MSMO1 gene was expressed in diabetic animal models and shown to play key roles in cholesterol biosynthesis, energy metabolism, obesity, and dyslipidemia regulation." (PMID 30781724, 2019).
Psoriasiform dermatitis (4 papers, 2013 to 2026). A skin abnormality characterized by redness and irritation, with thick, red skin that displays flaky, silver-white patches (scales). "MSMO1 deficiency has been linked to psoriasiform dermatitis." (PMID 41380997, 2025). "Background and Clinical Significance: MSMO1, encoding a key enzyme in the cholesterol synthesis pathway, is associated with an autosomal recessive condition characterized by microcephaly, ocular abnormalities, growth delay, psoriasiform dermatitis, immune dysfunction, and intellectual disability." (PMID 41718295, 2026).
cervical squamous cell carcinoma (3 papers, 2021 to 2023). A squamous cell carcinoma arising from the cervical epithelium. "In addition, the risk degree diagram in GEPIA2 suggested that the MSMO1 was a high-risk gene in cervical squamous cell carcinoma." (PMID 34759952, 2021). "A previous study revealed that MSMO1 plays crucial roles in tumorigenesis and progression and is a promising prognostic biomarker for cervical squamous cell carcinoma." (PMID 38022627, 2023). "Our study also probed how the expression of MSMO1 in cervical squamous cell carcinoma was related to the level of immune infiltration." (PMID 34759952, 2021). "The result showed that differential expression of MSMO1 was statistically significant in cervical squamous cell carcinoma." (PMID 34759952, 2021). "The results showed that the expression of MSMO1 differed significantly in the different stages of cervical squamous cell carcinoma, and the higher the stage the higher the expression (F value = 4.1)." (PMID 34759952, 2021). "Therefore, we investigated the clinical significance of MSMO1 in cervical squamous cell carcinoma based on bioinformatics analysis." (PMID 34759952, 2021). "Therefore, this study uses tumor data from TCGA, GEO, and other websites to research the expression and clinical significance of MSMO1 in cervical squamous cell carcinoma." (PMID 34759952, 2021). "However, there are currently few studies on MSMO1 in cervical squamous cell carcinoma or other solid cancers." (PMID 34759952, 2021).
atherosclerosis (2 papers, 2017 to 2020). A disease characterized by the build-up of fatty material and calcium deposition in the arterial wall resulting in partial or complete occlusion of the arterial lumen. "We found 18 compounds in GBH and 213 atherosclerosis-related genes in one huge network (exceptions were β-sitosterol α1 (compound) and MSMO1 (gene))." (PMID 33321972, 2020).
cervical cancer (2 papers, 2021 to 2022). A primary or metastatic malignant neoplasm involving the cervix. "Furthermore, HPA database tissue results showed that compared with normal cervical tissue, malignant cell proliferation was more obvious in tumor tissue, so MSMO1 had an effect on cervical cancer tissue (p < 0.01)." (PMID 34759952, 2021). "From this, we can infer the potential role of miRNAs targeting MSMO1 in cervical cancer." (PMID 34759952, 2021). "Moreover, miRNA was also related to drug resistance and may play a role in the treatment of cervical cancer when combined with other drugs, suggesting that MSMO1 may also affect drug resistance." (PMID 34759952, 2021). "After multivariate Cox regression analysis, eight genes were identified as key predictors of HLA-G-driven DEGs in the prognostic risk model for predicting the overall survival of patients with cervical cancer, including CD46, LGALS9, PGM1, SPRY4, CACNB3, PLIN2, MSMO1, and DAGLB." (PMID 35924232, 2022). "Moreover, the abnormal expression of MSMO1 in muscular mice cervical cancer was one of the factors that affected the human papillomavirus type 16 E6 transgenic model (K14E6), which could speculate that MSMO1 may lead to female cervical cancer." (PMID 34759952, 2021).
osteosarcoma (2 papers, 2025 to 2026). A usually aggressive malignant bone-forming mesenchymal neoplasm, predominantly affecting adolescents and young adults. "Taken together, these findings support a model in which MSMO1 shapes osteosarcoma behavior through coordinated regulation of sterol metabolism, Wnt/β-catenin–c-MYC signaling, and glutamine catabolism." (PMID 41463320, 2025). "Given the limited understanding of MSMO1 in osteosarcoma, we prioritized this gene for mechanistic interrogation." (PMID 41463320, 2025).
pancreatic cancer (2 papers, 2022 to 2024). "In humans, mutations in the MSMO1 gene have been linked to diseases such as pancreatic cancer, whereas in livestock, MSMO1 appears to influence fat deposition in chickens and ducks." (PMID 39765715, 2024). "Until now, the potential function and pathway of MSMO1 in the development of pancreatic cancer (PC) has not been explored yet, to our knowledge." (PMID 36046654, 2022).
Sepsis (2 papers, 2023 to 2024). Sepsis is defined as life-threatening organ dysfunction caused by a dysregulated host response to infection.
cutaneous sarcoidosis (1 paper, 2024).
dermatitis (1 paper, 2023). An inflammatory process affecting the skin. "Mutations in the MSMO1 gene, which encodes the sterol-C4-methyl oxidase (SMO), and the NSDHL gene can cause psoriasis-like dermatitis, inflammatory cell infiltration, and the accumulation of meiosis-activating sterol (MAS), an intermediate product of cholesterol metabolism, in the skin of patients." (PMID 37234169, 2023).
developmental delay (1 paper, 2026). "Case Presentation: This report describes a patient presenting with global developmental delay and bilateral infantile cataracts found to harbor a homozygous likely pathogenic MSMO1 variant and reviews the literature on MSMO1 deficiency and its association with infantile cataracts." (PMID 41718295, 2026).
esophageal cancer (1 paper, 2022). A primary or metastatic malignant neoplasm involving the esophagus. "However, MAGEA6 positively regulates MSMO1 and facilities the capacity of migration and invasion in esophageal cancer cells." (PMID 36046654, 2022).
gastric cancer (1 paper, 2022). A primary or metastatic malignant neoplasm involving the stomach. "Down-regulation of MSMO1 was significantly associated with poor prognosis in liver cancer 20 and worse 5-years overall survival rates in gastric cancer." (PMID 36046654, 2022).
hepatocellular carcinoma (1 paper, 2021). A malignant tumor that arises from hepatocytes. "In human hepatoma cells, the major transcription regulator of lipid metabolism PPARα incorporates with SREBP in regulating MSMO1 expression." (PMID 34759952, 2021). "Another study showed that MSMO1 was the target of the miR-23 family and might be used as candidate biomarkers of JFH-1-infected hepatocellular carcinoma." (PMID 34759952, 2021).
lymph-node metastasis (1 paper, 2022). "MSMO1 positive expression was negatively associated with T stage, lymph node metastasis and vascular permeation of PC patients." (PMID 36046654, 2022). "In current study, high MSMO1 expression was negatively relevant with T stage (P=0.025), lymph-node metastasis (P=0.046) and vascular permeation (P=0.009) of 92 PC patients, patients with low MSMO1 expression had a poor prognosis shown by Kaplan-Meier curve (P=0.01)." (PMID 36046654, 2022).
nasopharyngeal carcinoma (1 paper, 2022). A carcinoma arising from the nasopharyngeal epithelium. "Not coincidentally, a recent report has indicated that MSMO1 might contribute to stemness maintenance of nasopharyngeal carcinoma cells." (PMID 35813482, 2022).
phospholipidosis (1 paper, 2023). "In particular, the upregulation of the genes MSMO1, IDI1, LSS, and HMGCR suggested enhanced synthesis of cholesterol, and the upregulation of FASN suggested an increased synthesis of fatty acids that may in turn induce phospholipidosis." (PMID 37745076, 2023).
sarcoidosis (1 paper, 2024). Sarcoidosis is a multisystemic disorder of unknown cause characterized by the formation of immune granulomas in involved organs.
cancer (15 papers, 2018 to 2025). A tumor composed of atypical neoplastic, often pleomorphic cells that invade other tissues. "Several researches have implicated the clinical significance of MSMO1 expression in various cancers." (PMID 36046654, 2022). "Methylsterol monooxygenase 1 (MSMO1), an intermediate enzyme involved in cholesterol and fatty acid biosynthesis, acts as a novel mediator of chemoresistance in cancer." (PMID 38022627, 2023). "Due to the different kinds of cancer and the related cellular environment, the function and mechanism of MSMO1 would be different and even contrary in various cancers." (PMID 36046654, 2022). "The query of gene expression in the Oncomine database showed that MSMO1 was highly expressed, which was also found in the comparison of Biewenga Cervix and Pyeon multi-cancer data." (PMID 34759952, 2021). "MSMO1 was highly expressed in tumor tissue of BC compared with adjacent normal tissue in the cancer genome atlas (TCGA) dataset." (PMID 34893642, 2021). "MSMO1, a typical target of cholesterol biosynthesis, has been discovered to be up-regulated in correlation with drug resistance, tumor cell proliferation, and suppression of apoptosis in several cancers." (PMID 41463320, 2025). "Moreover, we created MSMO1 and DHCR7 knockdown cancer cells and discovered that MSMO1 or DHCR7 inhibition rescued the Az-induced increase in HLA-ABC." (PMID 38715057, 2024). "Nowadays, the potential role of MSMO1 in cancer cells is still controversial." (PMID 36046654, 2022). "We also evaluated the expression of MSMO1 by the qRT-PCR assay in an independent BC cohort from Fudan University Shanghai Cancer Center (FUSCC), and we found that high MSMO1 expression was significantly associated with poor disease-free survival (DFS, p = 0.0007)." (PMID 34893642, 2021). "MSMO1 is also believed to be involved in cholesterol metabolism and cancer." (PMID 30568916, 2018). "Thus, co-expressed genes and miRNA might affect the expression of MSMO1, and MSMO1 might have a potential impact on the tumor immunity, indicating that MSMO1 can be used as a promising cancer candidate biomarker." (PMID 34759952, 2021). "Taking these findings into account, MSMO1 might be correlated with immunity in cancer." (PMID 34759952, 2021). "In human cancer cells, PPAR-α, a key transcriptional regulator of lipid metabolism, cross-talks with SREBP to regulate the expression of Hmgcs1 and Msmo1." (PMID 39062636, 2024). "Previous research has shown that, in cancer, SCD1 protein expression positively correlates with methylsterol monooxygenase 1 (MSMO1) expression and can confer ferroptosis resistance." (PMID 35805147, 2022). "The R code and Perl language tools were used to collate and analyze the gene expression profile data of cancer tissues and para-cancerous tissues of CESC patients in the TCGA database for obtained differential genes including MSMO1." (PMID 34759952, 2021). "Recent studies demonstrated that MSMO1 has participated the development of various cancer, however, its role in prostate is not reported." (PMID 38459501, 2024). "And thus, it might be valuable to investigate the role of MSMO1 in HNSCC and even varieties of cancers in the future." (PMID 35813482, 2022). "In addition, the increased expression of MSMO1, HMGCS1, MVD, and SREBF2 across solid tumors vs. normal tissues based on the analysis of TCGA datasets further signifies the crucial role of these metabolic genes in multiple cancers." (PMID 37745085, 2023).
tumor (13 papers, 2007 to 2025). "Overall, this discovery provides clues for understanding the regulatory role of MSMO1 in the tumor immune microenvironment." (PMID 41463320, 2025). "MSMO1 acts as a tumor suppressor via inhibiting the aggressive malignant biology of PC accompanying with regulating EMT and PI3K/AKT signaling." (PMID 36046654, 2022). "In vivo, subcutaneous tumor size was enhanced by MSMO1 silencing following with the consistent change of EMT and PI3K/AKT signaling shown in vitro." (PMID 36046654, 2022). "In histology, tumor tissues were observed by HE staining, besides, MSMO1 and E-cadherin expression were decreased but β-catenin, Vimentin, p-PI3K (Tyr458) and p-AKT (Ser473) expression were increased in Tumor was further confirmed by IHC." (PMID 36046654, 2022). "In current study, MSMO1 is identified as a novel tumor suppressor in PC development involving a novel signaling axis of EMT and PI3K-AKT-mTOR pathway, which was not reported previously to our knowledge." (PMID 36046654, 2022). "We then checked that the expression level of MSMO1 was positively correlated with tumor purity, obtaining CD4 + T cells, a factor related to the cumulative survival rate of CESC over time." (PMID 34759952, 2021). "Previous study has indicated that the inactivation of MSMO1 markedly sensitized tumor cells to therapeutic anti-EGFR antibody via increased EGF receptor degradation." (PMID 34893642, 2021). "The present study systematically evaluated candidate signature gene MSMO1 and clarified the association between MSMO1 and CESC prognosis, as well as the correlation between MSMO1 and tumor immunity." (PMID 34759952, 2021). "The level of methylation MSMO1 was significantly increased in tumor tissues but there was an insignificant effect on the prognosis." (PMID 34759952, 2021). "Extracellular acidic pH due to nutrient starvation activates SREBP2 to induce the expression of MSMO1, which contributes to tumor growth and malignancy." (PMID 33023006, 2020). "Meanwhile, As the degree of tumor differentiation enhancing, the expression of MSMO1 increases." (PMID 36046654, 2022). "Tumor volumes in MSMO1 siRNA group were much larger (P=0.0138)." (PMID 36046654, 2022). "We explored the level of methylation of MSMO1 in tumor tissues and normal tissues." (PMID 34759952, 2021). "We constructed the models of subcutaneous tumor by PANC02 cells which were transfected with MSMO1 siRNA and negative control (NC), respectively." (PMID 36046654, 2022). "In the Th17 lineage, RORC (receptor) is upregulated on the tumor infiltrating CD4+ T-cells and its ligands (CYP51A1, FDFT1, HSD17B7, LBR, TM7SF2, MSMO1, NSDHL) are also upregulated on the tumor cells, implying GBM expresses ligands that induces Th17 phenotype in tumor infiltrating helper T-cell." (PMID 34012510, 2021).
infection (8 papers, 2017 to 2025). The state of being infected such as from the introduction of a foreign agent such as serum, vaccine, antigenic substance or organism. "Owing to the reoxygenation, expression of the SREBP2 target MSMO1 was not elevated in hypoxia-primed THP-1 cells after infection." (PMID 37377965, 2023).
MSMO1 also shares sentences with these, for which no sentence is quoted: Obesity (3 papers); lung carcinoma (2); melanoma (2); microcephaly (2); Anxiety (1); breast tumors (1); cardiovascular diseases (1); cataract (1); colorectal cancer (1); congenital cataracts (1); congenital hemidysplasia with ichthyosiform erythroderma and limb defects (1); cutaneous leishmaniasis (1); dermatomycosis (1); Granuloma (1); Greenberg dysplasia (1); Hepatic steatosis (1); Huntington disease (1); hypopharyngeal cancer (1); hypotrichosis (1); immune dysfunction (1); Insulin resistance (1); Intellectual disability (1); lathosterolosis (1); liver cancer (1); metabolic disease (1); psoriasis (1); skeletal dysplasia (1); Smith-Lemli-Opitz syndrome (1); systemic lupus erythematosus (1); type 2 diabetes (1).
A further 3 diseases each share a sentence with MSMO1 in 1 paper.